ARG1 (arginase 1)
Diseases named in the same sentence as ARG1 in open-access papers (continued):
Sharing a sentence is not in itself a finding about the gene and the disease.
Stroke (continued). "The mRNA levels of M2 markers (Arg-1, Ym-1) increased at 24 h, peaked at 3 d after stroke and then began to decrease; while the mRNA levels of M1 markers (CD16, CD86) gradually increased over time from 3 d and remained elevated for at least 14 days after tMCAO28." (PMID 27775054, 2016). "Interestingly, in a recent study on ischaemic stroke, Arg1 was reported to have unexpected detrimental influences on infiltrating macrophages by modulating microglial function and synaptic pruning in the peri-infarct region, affecting post-stroke recovery." (PMID 41488750, 2025). "Notably, ARG1 emerged as the most significantly upregulated gene in stroke samples." (PMID 40313968, 2025). "Indeed, the STAT6/Arg1 pathway modulates microglia/macrophage phenotype while activation of STAT6 has been reported in macrophages around the ischemic lesion early after experimental stroke in mice but also in stroke patients." (PMID 36818562, 2023). "In addition, stroke patients with increased ARG1 are more likely to be infected and have a poor prognosis, which may be related to the immune suppression caused by the stroke." (PMID 35419117, 2022). "This implies that Arg1 may affect stroke progression by modulating the cerebral immune response." (PMID 36361836, 2022). "Thus Arg1+ microglia/macrophages from the first two days of stroke were retained." (PMID 36361836, 2022). "A subpopulation of arginase 1 (Arg1)-expressing microglia exhibits an anti-inflammatory phenotype, with expression of IL-10 and TGF-β, and promotes recovery from stroke injury." (PMID 38550920, 2024). "Conversely, M2-type microglia are characterized by their production of IL-10, transforming growth factor-β (TGF-β), arginase-1 (Arg-1), and vascular endothelial growth factor (VEGF), which facilitate recovery following stroke." (PMID 37597109, 2023). "In our previous study, MANF, a paralogous protein of CDNF, was shown to increase the density of ARG1+ and CD68+ cells in subcortical regions after stroke." (PMID 36792604, 2023). "In particular, microglia exhibited a dominant neuroprotective M2-like response (phagocytosis and tissue repair) for the first seven days post stroke, characterized by increased expression levels of CCL22, IL10, CD206, arginase-1 and TFG-β." (PMID 34194419, 2021). "In humans, ARG1 mRNA expression and ArgI serum activity correlate with neutrophil-to-lymphocyte ratio (NLR) and stroke severity in stroke patients." (PMID 34092245, 2021). "The expression of M1 (MCP-1, iNOS, CD32, CD86 and IFN-γ) and M2 (Ym1/2, Arg-1, CD206, BDNF and TGF-β) markers was significantly increased in vehicle-treated stroke mice 1, 3, 7, and 14 days after MCAO." (PMID 31434993, 2019). "The expression of M1 markers (TNF-α, IL-12, CD16, CD32 and iNOS) and M2 markers (Arg-1 and YM1/2) were all significantly increased in vehicle-treated stroke mice 3 days after dMCAO." (PMID 28785217, 2017). "As comparison, in one of the original studies on stroke, a 9-gene signature was derived, including S100A12, ARG1 and MMP9 of our BRGs." (PMID 28771541, 2017). "Our study suggests a novel relationship between ARG1, NLR, and stroke severity, and the NLR is an underutilized clinically available biomarker to monitor the post-stroke immune response." (PMID 26515089, 2016). "In the adult rodent, M1 markers (iNOS, CD11b, CD16, and CD32) were still elevated at 14 days after stroke, while M2 markers (CD206, Arg-1, Ym1/2 and IL-10) were decreased at 7 days after ischemia." (PMID 27126393, 2016). "There was also a statistically significant relationship between ARG1 and NIHSS (p = 0.001), adjusting for age, sex, diabetes, prior stroke, and heart disease." (PMID 26515089, 2016). "Future studies will need to address the functional relationships between ARG1 and NLR post-stroke to test novel immune modulating therapeutic strategies for stroke patients." (PMID 26515089, 2016).
Stroke (continued). "In the future study, analyzing additional markers for inflammatory MG, such as CD16 and IL-1α, and anti-inflammatory MG, such as Arg1 and YM1, would further strengthen the essential role of endogenous Nrf2/HO-1 axis activation in modulating MG polarization after stroke." (PMID 39469715, 2024). "We have shown that Arg1-positive (arginase 1) and phagocytic CD68-positive cells are increased after viral vector-mediated MANF gene delivery in a rat dMCAo cortical ischemic stroke model, coinciding with elevated brain repair processes after stroke." (PMID 35783104, 2022). "In stroke, the STAT6/Arg1 pathway was found to induce efferocytosis by Mφs/microglia." (PMID 35488301, 2022). "The percentage of Arg1+ Mo-MDSCs was inversely correlated to age on day 5 (r = −0.7228, p = 0.0182) after stroke (data not shown)." (PMID 33329318, 2020). "qPCR analysis of the PI area in the stroke brains at 3 dpi revealed a significant increase of major alternative activation markers Arg1 (p = 0.0408) and Ym1 (p = 0.0122), but not Fizz1/Rentla (data not shown) upon IL-13 treatment." (PMID 31372938, 2019). "Further distinction between recruited brain-resident microglia and infiltrated systemic macrophages following stroke and MSC transplantation in CX3CR1eGFP/+ CCR2RFP/+ double transgenic mice revealed that about two thirds of Arg-1+ cells are infiltrated macrophages." (PMID 29866203, 2018). "On the other hand, Arg1+CD8+CD68+ cells increased until day 3 but declined thereafter and proportion wise, iNOS+CD8+CD68+ cells became the most dominant CD8+CD68+ cell type at day 4 after stroke." (PMID 29342151, 2018). "Our study suggests a novel relationship exists between ARG1, NLR, and stroke severity which may help guide future mechanistic studies of post-stroke immune suppression." (PMID 26515089, 2016). "M2 microglia markers Il4, Arg1, and Fam19a3 were not changed by either hypertension or stroke." (PMID 38886874, 2024). "Thus, it is possible that IFNAR1 signaling induces STAT3 activation, leading to the suppression of tPA-enhanced inflammatory molecules, IL-1α, IL-1β and CD86, expression and the promotion of anti-inflammatory molecules, Arg1 and CD206, upregulation in MG in delayed tPA-treated stroke animals." (PMID 37063896, 2023). "Importantly, depleting microglia induced a significant increase in the mRNA expression level of anti-inflammatory factors TGF-β1, Arg1, IL-10, IL-4, and Ym1 as well as a significant decline of pro-inflammatory factors TNF-α, iNOS, and IL-1β 3 days after stroke." (PMID 33757565, 2021). "Furthermore, because post-stroke immunosuppression persists for a period time in AIS recovery, ARG1 inhibition may have a beneficial effect on AIS severity and outcome even administered at a later time point than recanalization agents, such as rTPA." (PMID 26515089, 2016). "In addition, the characteristic marker genes of M2-type microglia (such as Arg1, Ym1) had not been fully expressed yet, indicating that the differentiation of M2-type microglia is delayed compared with M1 type at the early stage of a stroke." (PMID 33692998, 2021). "Thus, ARG1 and MMP9 may be used in monitoring the recovery from stroke." (PMID 28771541, 2017).
diabetes (41 papers, 2013 to 2025). "Serum extracellular vesicle (EV)-derived arginase 1 (ARG 1) plays a critical role in diabetes-associated endothelial dysfunction." (PMID 35277141, 2022). "They found increased levels of arginase 1 in patients with diabetes carrying the variant genotypes of both SNPs." (PMID 34830689, 2021). "In conclusion, this is the first report discussing the effect of ARG1 polymorphism on the microvascular complications that are associated with diabetes." (PMID 34830689, 2021). "Studies have demonstrated that polymorphic variants of arginase 1 gene (ARG1) are involved in human diseases, such as coronary heart disease, hypertension, and diabetes." (PMID 34830689, 2021). "In conclusion, to the best of our knowledge, this is the first published study analyzing the effect of the ARG1 gene polymorphism on the microvascular complications of diabetes." (PMID 34830689, 2021). "The results of previously conducted animal studies show that arginase 1 is associated with endothelial dysfunction in hypertension, aging, diabetes, and ischemia." (PMID 34830689, 2021). "Previous studies in models of diabetes and diabetic retinopathy have shown that increases in arginase 1 expression are associated with cell stress and vascular dysfunction." (PMID 29673160, 2018). "Subsequently, Alia and Munther (2017) proposed that high level of arginase -1 is associated with increased risk of diabetes mellitus and cardiovascular disease." (PMID 30233283, 2018). "After adjusting for age, hypertension, smoking, heart disease, sex, hyperlipidemia, and diabetes, we observe that serum ARG1 activity has a statistically significant association with NIHSS (p = 0.027)." (PMID 26515089, 2016). "Elevated Arg1 expression has been associated with cell proliferation and endothelial dysfunctions during ischemia/reperfusion injury, aging, and diabetes." (PMID 23977269, 2013). "Diabetes and high glucose models in vitro and in rodents have been associated with increased arginase activity and increased expression of both arginase isoforms, arginase-1 and arginase-2." (PMID 40076703, 2025). "Several studies have demonstrated tangible mRNA therapies, such as the regeneration of VEGF-A protein for diabetes, restoration of tumor suppressors for cancer treatment, delivery of ARG1 mRNA liver-targeted NPs for arginase deficiency, and mRNA vaccines for COVID-19 by Moderna, Inc." (PMID 37264406, 2023). "EVs derived from RBCs (RBC-EVs) of patients with diabetes were taken up by the endothelium and were able to impair endothelium-dependent relaxation via an EV-mediated transfer of the prooxidant enzyme arginase-1 (Arg1) from RBCs to endothelial cells." (PMID 40371651, 2025). "In diabetes and oxidative stress environments, increased expression of arginase-1 leads to the hydrolysis of L-arginine into urea and L-ornithine." (PMID 39126007, 2024). "In contrast with the proinflammatory response, kidney gene expression of the anti-inflammatory marker Arginase-1 was unaffected by diabetes, but was increased 20-fold at day 10 after IRI, which then declined to 3-fold at day 28 after IRI." (PMID 38391050, 2024). "The downregulated genes in cluster 9 in the diabetes group on day 1 including Arg1, Cxcl3, Plac8, Saa3 were enriched in response to external biotic stimulus, response to other organism, response to biotic stimulus, defence response (Supplementary 11)." (PMID 36445632, 2023). "Together, these results suggest that Arg1 plays a role in diabetes-induced endothelial dysfunction in retinal vasculature." (PMID 35250632, 2022). "Despite the prominent role of Arg1 in diabetes-induced endothelial dysfunction, a neuroprotective role of Arg1 has been surprisingly revealed in murine models of retinal ischemia/reperfusion injury (I/R)." (PMID 35250632, 2022). "What is more, Hiru partially reverses the downregulated Arg-1 expression in streptozotocin-induced diabetes." (PMID 35496058, 2022).
diabetes (continued). "Pernow and his co-workers presented evidence of the high-level expression and activation of ARG1 in the vascular endothelium of type-2 diabetes mellitus patients." (PMID 33918732, 2021). "In mouse and rat models, an increase in the expression of arginase 1 that is induced by diabetes was shown to be involved in the high glucose-induced deterioration of retinal blood flow by means of the vascular endothelial dysfunction mechanism." (PMID 34830689, 2021). "Upregulation of ARG1, particularly, is prominent in myocardial infarction, diabetes, hypertension, and Alzheimer's disease." (PMID 32149110, 2020). "In vivo studies were performed using wild type mice as well as arginase 1 knockout specific in endothelial cells (EC-A1–/–) of control mice, diabetes mice and diabetes mice treated with HGWWD (60 g crude drugs/kg/d) for 2 weeks." (PMID 32269530, 2020). "In order to assess the involvement of arginase 1 expression in this premature senescence phenotype we determined the impact of diabetes on SA β-Gal activity in vessels isolated from arginase 1 heterozygous knockout mice (A1+/−)." (PMID 29673160, 2018). "The present study was undertaken to investigate the specific involvement of arginase 1 in diabetes-induced premature retinal EC senescence." (PMID 29673160, 2018). "The findings of the current study are consistent with previous reports showing that hyperglycemia and diabetes mellitus lead to the up-regulation of arginase-1, resulting in reduced nitric oxide-mediated dilation in human coronary arteries." (PMID 30233283, 2018). "Other studies have shown that the inhibition or knockdown of p38 MAPK blocks elevation of arginase 1 expression/activity in conditions of diabetes and angiotensin II-induced endothelial dysfunction." (PMID 29673160, 2018). "We have recently found that diabetes-induced premature senescence of retinal endothelial cells is accompanied by NOX2-NADPH oxidase-induced increases in the ureohydrolase enzyme arginase 1 (A1)." (PMID 29673160, 2018). "Our studies have shown that knockdown of arginase 1 also prevents the diabetes-induced increases in ROS formation while preserving NO bioavailability and limiting vascular inflammation." (PMID 28617308, 2017). "We found that diabetes- or high glucose-induced increases in NOX2/NADPH-generated ROS induce premature EC senescence by a mechanism involving increases in arginase 1 expression and activity and decreases in NO bioavailability." (PMID 28617308, 2017). "These experiments showed that diabetes-induced increases in arginase 1 expression and arginase activity were completely blocked in diabetic NOX2−/− mice, indicating that NOX2 expression has a key role in this process." (PMID 28617308, 2017). "After AIC model selection, adjusting for age, hypertension, and diabetes, there is a statistically significant relationship between serum ARG1 activity and NLR (p = 0.009)." (PMID 26515089, 2016). "After AIC model selection, there was a statistically significant association between ARG1 and NLR (p = 0.019), adjusted for age, hypertension, and diabetes." (PMID 26515089, 2016). "We have demonstrated that streptozotocin (STZ) diabetic mice with partial knockout of Arg1 are protected against diabetes-induced vascular dysfunction compared to WT mice." (PMID 23977269, 2013). "Given that, the individual impact of CAD and diabetes affecting expression of arginase-1 cannot be examined in this study." (PMID 24133491, 2013).
diabetes (continued). "Protein expression of arginase-1 in small coronary arteries was significantly higher in patients with diabetes." (PMID 24133491, 2013). "Further studies involving higher number of research subjects are needed to assess the independent impact of increased arginase-1 expression on coronary artery responsiveness in diabetes." (PMID 24133491, 2013). "Several studies have established that RBCs play a significant role in mediating ED in various pathological conditions, including diabetes mellitus and hypercholesterolemia, primarily due to elevated levels of arginase 1 and increased reactive oxygen species (ROS) formation in endothelial cells." (PMID 41158731, 2025). "Arginase-1 has been shown to be involved in the development of diabetes and it has been shown to be involved in insulin resistance by several mechanisms, including alterations of the balance between M1 and M2 macrophages and alteration of macrophage infiltration into fat tissue." (PMID 37810891, 2023). "Interestingly, in pathologies characterized by increased RBC arginase-1 activity, like diabetes, there is also increased oxidative stress and ROS generation." (PMID 33806028, 2021). "To assess the role of arginase in diabetes/hyperglycemia-induced senescence of retinal microvascular ECs, we determined the effect of high glucose (HG) treatment on senescence of retinal ECs in relation to arginase 1 expression." (PMID 29673160, 2018). "Genetic polymorphisms mapped in the ARG1 locus (chr6:131894344-131905472) and their functional effects on type 2 diabetes mellitus (T2DM) have not been thoroughly elucidated to date." (PMID 30233283, 2018). "Data from current study showed that arginase-1 and variants of ARG1 may be associated with increased risk of promoting an inflammatory response as evidenced by elevated CRP levels in type 2 diabetes mellitus." (PMID 30233283, 2018). "The probable functional SNPs (rs2781665 and rs2781666) mapped in the promoter region of the ARG1 gene are known to be involved in genetic regulation, but in terms of association studies, ARG1 polymorphism has not been shown in subjects with vascular complications like diabetes mellitus (DM)." (PMID 30233283, 2018). "However, Arg1 expression was down-regulated in our model of diabetes, which was contradictory to the previous report." (PMID 29394254, 2018). "However, this study is the first we know of to show a link between NOX2, arginase 1 and diabetes-induced retinal endothelial cell senescence." (PMID 28617308, 2017). "Although this work provides proof-of-concept evidence on the role of RBC-EVs from patients with diabetes, there is a lost opportunity to study the effects of RBC-derived Arg1 in vivo, a condition which better reflects features of the diabetic microenvironment." (PMID 40371651, 2025). "Inhibition of ARG1 with ABH therapy avoided the decline of NO and significantly reduced the incidence of diabetes and obesity-induced bone complications." (PMID 36338341, 2022). "In contrast, approximately 80% of the NOD-HET remained diabetes free, and this was accompanied by reduced iPLA2β (~65%) and TNF-α production by CD4+ T cells and higher M2 marker, Arg1, relative to NOD." (PMID 32814707, 2020). "The notion that an external source of Arg1 precipitates endothelial dysfunction is supported by previous work showing that endothelial ablation of Arg1 in mice does not rescue diabetes-induced endothelial dysfunction." (PMID 40371651, 2025). "Our group has shown that diabetes induced impairment of retinal blood flow was attenuated in diabetic mice lacking one copy of arginase 1 or diabetic mice treated with arginase inhibitor." (PMID 29673160, 2018). "A 24-day treatment with the arginase-1 inhibitor nor-NOHA aimed to further upregulate the citrulline-NO pathway unexpectedly reduced the incidence of autoimmune diabetes in older diabetes-prone female NOD mice." (PMID 29450408, 2018).
diabetes (continued). "Therefore, the absence of a clear phenotype in RBC Arg1 KO mice may thus reflect this low baseline expression under homeostatic healthy conditions and the lack of disease conditions like diabetes, cancer or infection." (PMID 40729962, 2025).